OR1L8 (olfactory receptor family 1 subfamily L member 8)
Description:
Odorant receptor.
Synonyms: OR9-24
Tractability: Small molecule: it belongs to a druggable protein family. Antibody: UniProt places it where antibodies can reach, with medium confidence; UniProt predicts a signal peptide or a membrane-spanning region; its Gene Ontology location is reachable by antibodies, with medium confidence.
Gene: Protein-coding gene on chromosome 9 (122,567,117 to 122,583,384, reverse strand). Ensembl gene ENSG00000171496.
Subcellular location: Cell membrane
Pathways (Reactome):
Sensory Perception: Expression and translocation of olfactory receptors
Gene Ontology:
Molecular function: olfactory receptor activity; G protein-coupled receptor activity; signaling receptor activity
Biological process: signal transduction; detection of chemical stimulus involved in sensory perception of smell; G protein-coupled receptor signaling pathway; sensory perception of chemical stimulus
Cellular component: plasma membrane; membrane
Genetic constraint (gnomAD): Loss-of-function variants: 0 observed, 1.93 expected, observed/expected ratio (o/e) 0, 90% interval 0 to 1.38. That is too few expected variants to judge how well the gene tolerates losing a copy. Missense variants: 323 observed, 390.34 expected, observed/expected ratio (o/e) 0.83, 90% interval 0.75 to 0.91. Synonymous variants: 148 observed, 153.12 expected, observed/expected ratio (o/e) 0.97, 90% interval 0.85 to 1.11.
Homologues: Orthologues: chimpanzee OR1L8 (95% identical), rat Or1l8 (84% identical), dog OR1L8 (80% identical). Paralogues in human: OR1L1 (69% identical), OR1L3 (68% identical), OR1L6 (62% identical), OR1L4 (61% identical), OR1F1 (55% identical), OR1N2 (53% identical), OR1J2 (53% identical), OR1I1 (52% identical), OR7C1 (52% identical), OR1M1 (51% identical), OR1J1 (51% identical), OR1C1 (50% identical), and 116 more.